PLD1 (phospholipase D1)
Diseases named in the same sentence as PLD1 in open-access papers (continued):
Sharing a sentence is not in itself a finding about the gene and the disease.
tumor (52 papers, 2007 to 2025). "Treatment with PLD1 inhibitors significantly decreases tumor growth in mice bearing PDXs with PIK3CA and KRAS mutations and in mice bearing PDXs with APC and KRAS mutations." (PMID 38945955, 2024). "The immunohistochemistry (IHC) results from the CC tissue microarray (TMA) analysis showed that the increased expression of PLD1 was significantly associated with a tumour size >2 cm and parametrial infiltration." (PMID 35775110, 2022). "Based on our data, the decreased expression of DUSP7 and increased expression of PLD1 were significantly associated with a tumour size >2 cm and parametrial infiltration." (PMID 34435746, 2021). "Third, LINC00511 can accelerate tumor progression through regulating several tumor-associated signaling pathways such as RXRA/PLD1, PTEN/AKT/FOXO1, p38, ERK1/2 and JNK pathways." (PMID 32713253, 2020). "After adjusting from tumor size, grading, and stage, multivariate analyses showed that PLD1 expression was an independent risk factor for survival." (PMID 26250158, 2015). "The IHC results from the CC TMA analysis showed that the decreased expression of DUSP7 (p = 0.045 and 0.044, respectively) and increased expression of PLD1 (p = 0.046 and 0.028, respectively) were significantly associated with a tumour size >2 cm and parametrial infiltration." (PMID 34435746, 2021). "Phospholipase D (PLD), especially its isoforms PLD1 and PLD2, is implicated in tumor malignancy, GSC maintenance, and resistance to therapies." (PMID 40565099, 2025). "Intestinal epithelial cell-specific PLD1 overexpression in ApcMin/+ mice increases nuclear β-catenin levels and tumor development." (PMID 38945955, 2024). "PLD1 inactivation decreases the expression of C-IC markers and the self-renewal capacity of C-ICs for serial tumor initiation and suppresses chemoresistance." (PMID 38945955, 2024). "The upregulation of miR‐320a and miR‐4496 by PLD1 inhibition attenuates self‐renewal, tumor‐initiating capacity, and chemoresistance." (PMID 38945955, 2024). "Phospholipase D (PLD) isoforms PLD1/2 promote tumor metastasis by catalyzing the hydrolysis of phosphatidylcholine to produce phosphatidic acid (PA)." (PMID 38495881, 2024). "Que decreased the level of Phospholipase D1 (PLD-1) enzyme that is associated with proliferation and suppression of apoptosis in tumor cells." (PMID 36986827, 2023). "Orthotopic BALB/c tumor mouse models were used to elucidate the effect of PLD1 inhibition on the pancreatic microenvironment." (PMID 37381714, 2023). "Animals deficient in another PC-PLD gene isoform, PLD1, or treated with a small-molecule inhibitor of PLD1 activity, exhibited reduced tumor growth, angiogenesis, and metastasis." (PMID 35250970, 2022). "The combination of a PLD1 inhibitor with PD-L1 blockade treatment further promoted antitumor immunity via cytotoxic CD8+ T-cell activation in the tumor environment relative to monotherapy." (PMID 36131027, 2022). "Depletion of PLD1 in melanoma and lung carcinoma tumor microenvironments results in reduced tumor burden." (PMID 36362078, 2022). "Consistently, the targeting of both PLD1 and autophagy, synergizing in inducing tumor cell apoptosis and tumor regression, has been proposed as potential anticancer therapy." (PMID 34429143, 2021). "Subcutaneous tumour tissues from the CFL1 knockdown group showed less PLD1 staining than those from the control group." (PMID 33784016, 2021). "Mouse GL‐26 GBM were transplanted into the brains of syngeneic C57BL/6 mice, and the treatment of PLD1 inhibitor reduced tumor formation and significantly increased survival." (PMID 32869317, 2021). "Such tumor‐induced neovascularization was significantly suppressed by treatment with PLD1 inhibitor." (PMID 32869317, 2021). "Combinational treatment remarkably suppressed the intracranial tumor formation and increased survival compared with that of PLD1 inhibitor alone." (PMID 32869317, 2021).
tumor (continued). "The PLD1 inhibitor alone greatly reduced GBM tumor formation and increased the survival of mice intracranially implanted with CD44High GSCs." (PMID 32725633, 2020). "We also found that miR‐320a and miR‐4496 upregulated by PLD1 inhibition attenuated self‐renewal, tumor‐initiating capacity, and chemoresistance." (PMID 32725633, 2020). "Increased PLD1 activity and expression have been reported in various tumor tissues and cell lines, and inhibition of PLD1 activity can slow down the growth and metabolism of tumors." (PMID 32337269, 2020). "Recently, we have reported that PLD1 in vascular endothelial cells is involved in tumor growth through the promotion of tumor angiogenesis in mice." (PMID 29674728, 2018). "Ablation of PLD1 in the tumor environment suppressed the activation of Akt and MAPK (mitogen-activated protein kinase) signaling pathways by VEGF (vascular endothelial growth factor) in vascular endothelial cells." (PMID 28399876, 2017). "We provide evidence about the beneficial effect of PLD inhibitors [FIPI (dual PLD1/PLD2) or VU0155072-2 (PLD2 inhibitor)] on avoiding infiltration of tumor-helping macrophages and neutrophils." (PMID 27851813, 2016). "The combination of PLD1 and autophagy inhibition was shown to synergize in inducing tumor cell apoptosis and tumor regression, providing a potential rational target for anticancer therapy." (PMID 28083512, 2016). "Stable transduction of either PLD1 or PLD2 overexpression in a much less aggressive human breast cancer cell line boosted tumor growth in a SCID model." (PMID 27851813, 2016). "The generation of PLD1-deficient transgenic mice provided the opportunity of studying the role of PLD1 in the tumor microenvironment." (PMID 28083512, 2016). "Partly mediated by impaired activation of αIIbβ3 integrin in platelets, tumor cell–platelet interactions decreased in Pld1−/− mice, resulting in reduced seeding of tumor cells into the lung parenchyma." (PMID 28083512, 2016). "Due to the numerous migratory and invasive signaling networks stimulated by PLD1 and PLD1 substrates, PLD1 represents a viable upstream target for limiting tumor spread and metastatic progression." (PMID 25734659, 2015). "Taken together, these findings suggest a new role of the PH domain of PLD1 in tumor regression via targeting of HIF-1α." (PMID 25361009, 2014). "For instance, tumor promoters, such as phorbol myristate, stimulate selective PLD1 expression via the NFκB signaling pathway." (PMID 20711340, 2010). "We have reported that stable overexpression of either PLD1 or PLD2 in fibroblasts causes transformation and enhancement of tumor formation." (PMID 20711340, 2010). "Oestrogen receptor expression was determined from the pathology reports that accompanied each tumour specimen, and the expression of PLD1, phospho-Akt, phospho-mTOR, and CKs 5/17 was evaluated by IHC analysis." (PMID 17726467, 2007). "Seventeen tumours had a basal level of PLD1 expression (score of 1), whereas the other 10 tumours overexpressed PLD1 (score of 2 or 3)." (PMID 17726467, 2007). "Phospholipase D1 was overexpressed in 6 of the 28 ER-positive tumours and in 4 of the 11 ER-negative cases." (PMID 17726467, 2007). "Our data also show that most basal-like tumours express PLD1, and it has been shown that patients with these types of tumours suffer from poor prognosis." (PMID 17726467, 2007). "Of the 10 tumours that overexpressed PLD1, 5 were negative for phospho-Akt expression, and importantly, these 5 PLD1-positive tumours overexpressed phospho-mTOR (tumours 6–10)." (PMID 17726467, 2007). "We found that PLD1 was expressed in six ER-positive tumours; four of these tumours showed positive phospho-mTOR expression, and two were negative for phospho-Akt expression." (PMID 17726467, 2007). "Phospholipase D1 tends to be overexpressed in tumours that express high levels of CKs 5/17, markers of basal-like tumours, and others have shown basal-like tumours are frequently associated with poor prognosis." (PMID 17726467, 2007).
tumor (continued). "Lastly, five tumour specimens overexpressed both PLD1 and phospho-Akt, and two of these five tumours overexpressed phospho-mTOR." (PMID 17726467, 2007). "Phospholipase D1 mRNA levels were significantly greater (>0.25 arbitrary units) in tumours that scored high for CKs 5 and/or 17 expression (P<0.01)." (PMID 17726467, 2007). "PLD1 may serve as a potential therapeutic target due to PLD1-promoted tumor proliferation and migration." (PMID 37381714, 2023). "We measured tumor volumes during treatment until the tumor volumes reached 500 mm3, then calculated tumor rejection ratios to rule out proliferation interference caused by PLD1." (PMID 37381714, 2023). "PLD-1 produces phosphatidic acid (PA), which is associated with the activation of matrix metalloproteinase-2 (MMP-2), i.e., extracellular matrix proteins directly involved in tumor metastasis." (PMID 36986827, 2023). "Furthermore, combination therapy with a PLD1 inhibitor and an anti-PD-L1 antibody further enhanced tumor regression via immune activation in the tumor environment." (PMID 36131027, 2022). "Additionally, the immunohistochemistry results showed that PLD1 knockout improved the expression of E‐cadherin and inhibited the expression of vimentin in tumour tissues, indicating that PLD1 knockout inhibited the EMT process of CASKI cells in vivo." (PMID 35775110, 2022). "PLD1 is a critical downstream mediator of HRAS‐induced tumour formation." (PMID 35775110, 2022). "In addition, the elevated expression level of PLD1 was significantly related to a tumour size >2 cm and parametrial invasion." (PMID 35775110, 2022). "PLD1 depletion in the tumor microenvironment results in lower tumor burden and reduced metastasis." (PMID 36131027, 2022). "Moreover, PLD1’s role in the tumor microenvironment, which confers the ability to disrupt tumor angiogenesis in some studies, makes it an attractive target." (PMID 28083512, 2016). "Interestingly, this correlation analysis showed that mainly in the ICD clinical settings tumoural CALR levels positively correlated with the tumoural levels of phagocytosis-associated genes (especially PLA2G5, PLD1, RAB5A, VAMP7, STAB2)." (PMID 26314964, 2015). "In summary, we revealed that miR-638 functions as a tumor suppressor in GC through inhibiting PLD1." (PMID 26250158, 2015). "Furthermore, PLD1-PH led to significant tumor regression in tumor xenografts when compared to vector cells." (PMID 25361009, 2014). "Protein kinase C alpha is specifically linked to activation of PLD1 and PLD2; results show that a PKCα link to PLD is active in cell lines derived from both normal and tumourigenic epithelia, including P4E6 cells derived from an early tumour." (PMID 21266973, 2011). "Phospholipase D1 was overexpressed in 6 of 31 ER-positive tumours and 4 of 11 ER-negative tumours." (PMID 17726467, 2007). "Interestingly, 6 of the 10 tumours that overexpressed PLD1 are grade 3 tumours, and 5 of these tumours are among the 7 tumours that overexpress PLD1 along with phospho-mTOR." (PMID 17726467, 2007). "Phospholipase D1 was overexpressed in three of the four tumours that showed high CK5/17 expression." (PMID 17726467, 2007). "In the present study, the PLD1 was significantly downregulated in the cold season, which could effectively reduce the PA content in lipid metabolism, thereby inhibiting tumor cell genesis and proliferation through the Akt/mTOR signaling pathway and Wnt signaling pathway." (PMID 37833936, 2023). "Interestingly, PLD1-PH suppressed tumor progression and expression of HIF-1α and its target genes." (PMID 25361009, 2014). "Therefore, it is plausible that tumour cells with basal PLD1 mRNA/protein may still have altered PLD1 enzyme activity." (PMID 17726467, 2007). "Therefore, identification of new molecular pathways such as PLD1/PA/mTOR signalling that are constitutively active in such types of tumours may be useful in selecting alternative targeted therapies." (PMID 17726467, 2007).
tumor (continued). "As a target of the Wnt signaling pathway and a positive feedback regulator, β-catenin forms the β-catenin/TFC-4 complex by binding to TFC-4-binding sites (TBE) in the PLD1 structure, thus activating PLD to promote tumor cell proliferation and invasion." (PMID 37833936, 2023). "PLD1 inhibition affects tumor neovascularization and growth through AKT and MAPK downregulation, resulting in reduced tumor angiogenesis." (PMID 37370855, 2023). "We found that the PLD1 inhibitor elicited DAMP expression in tumor cells, which enhanced phagocytic activity and the subsequent processing and presentation of tumor antigens by macrophages." (PMID 36131027, 2022). "This profile of genes includes AGPAT3, AKR1B1, PLD1, and UGT8, all of which have previously been reported to be involved in tumor proliferation." (PMID 34568042, 2021). "PLD1 has been shown to interact with vascular endothelial cells and promote the release of vascular endothelial growth factor (VEGF) to the tumor microenvironment." (PMID 35127525, 2021). "PLD1 induced expression through the RAF/ERK and NF-κB signaling pathways, leads to MMP-9 increased secretion, which promotes tumor invasion and metastasis." (PMID 33718168, 2021). "We further investigated the effects of PLD1 depletion and/or TMZ on the tumor‐propagating capacity of GSCs." (PMID 32725633, 2020). "Although only four tumours scored positive for CK5 and/or CK17 expression, it is interesting to note that PLD1 was overexpressed in 3 of the 4 CK5/17-positive cases, the basal-like CK-expression pattern." (PMID 17726467, 2007). "Moreover, compared with vehicle treatment, PLD1 inhibition increased ICAT expression and reduced the expression of Wnt target genes in tumor tissues from the PDX group." (PMID 38945955, 2024). "Next, we assessed whether the expression of selected genes (FKBP1A, PLD1, and PSMA4) was correlated to the tumor stage." (PMID 38570626, 2024). "And in the hypoxic tumor microenvironment of HCC, CFL1 can be transcriptionally activated by hypoxia-inducible factor-1α (HIF-1α), and subsequently interacts with PLD1 to inhibit PLD1 ubiquitination degradation and stabilize its expression, thereby activating the AKT pathway." (PMID 36463115, 2022). "However, discordant results were observed in the expression of other genes such as PLD1, which was down‐expressed in MTX‐resistant tumour samples but was significantly overexpressed in MTX‐resistant xenografts." (PMID 30592148, 2019). "PLD1 is overexpressed in several cancers including HNSCC, where it activates Src kinase and mitogen activated protein kinase (MAPK), driving invadopodia formation, maturation, and tumor cell invasion." (PMID 25734659, 2015). "Data from our study identify an additional subset of patients with tumours that overexpress PLD1 and phospho-mTOR, but do not express constitutive levels of phospho-Akt." (PMID 17726467, 2007). "We show that PLD1 is expressed in a subset of phospho-Akt-negative tumours that maintain phospho-mTOR expression." (PMID 17726467, 2007). "Five PLD1-positive tumours were negative for phospho-Akt expression, but positive for phospho-mammalian target of rapamycin (mTOR) expression." (PMID 17726467, 2007). "Seven tumours showed positive phospho-Akt and negative PLD1 expression, and five of these tumours scored positive for phospho-mTOR." (PMID 17726467, 2007). "Finally, a role of PLD1 and PLD2 inducing exosome secretion in OC cells has also been recently proposed, suggesting that PLD2 may also influence the tumor microenvironment in OC." (PMID 38403587, 2024). "Thus, it is likely that PLD1 and PLD2 have differential roles in tumor immunity." (PMID 36131027, 2022). "In this study, the expression of vimentin was significantly decreased and that of E‐cadherin was increased in PC‐11 and PC‐40 cells, indicating that knockout of PLD1 could attenuate EMT progression in CASKI cells, and this phenomenon was observed in mouse tumour tissues in vivo." (PMID 35775110, 2022).
tumor (continued). "However, the functional role of PLD1 in the link between PLD1-mediated immune responses and tumor immunity has not been elucidated." (PMID 36131027, 2022). "The lack of PLD1 decreased the number of metastases and tumor size." (PMID 24103483, 2014). "Because tumors with high PLD1 expression exhibit relatively high gemcitabine resistance, we used subcutaneous patient-derived organoid (PDO)-based xenografts (PDOXs) and orthotopic mouse tumor models to determine whether Vu0155069 enhanced sensitivity to gemcitabine by reducing PLD1 activity." (PMID 37381714, 2023). "Besides, the interaction between tumor cells and platelets was impaired in mice lacking PLD1." (PMID 31001703, 2019).
infection (8 papers, 2015 to 2025). The state of being infected such as from the introduction of a foreign agent such as serum, vaccine, antigenic substance or organism. "PspA1 alone and the PspA1 + PlD1 mixture were also protective against infection; however, only 50% of the mice survived the challenge in each of these groups." (PMID 38096222, 2023). "It suggests that PLD1 may modulatehost cell complexes, favoring the infection." (PMID 40396329, 2025). "The expression of lipid metabolism related enzymes ACC, FASN, PLD1, p-PLD1, and SCD1 in Ad-Vp3-infected cells were significantly higher at 12 and 24 h, and significantly lower at 36, 48, and 72 h post-infection when compared with the Ad-Mock infected cells (p < 0.05)." (PMID 33718168, 2021). "To confirm and further define the requirement of PLD1-dependent processes for HIV-1 replication, in a separate experiment we determined the effects of PLD1i on the accumulation of viral cDNA products at 8, 16, and 24 h after infection." (PMID 26020637, 2015). "Moreover, PLD1 and CBL9 were up-regulated in wheat after BYDV-GAV infection, respectively." (PMID 29652829, 2018).
neurodegenerative disease (5 papers, 2017 to 2023). A disorder of the central nervous system characterized by gradual and progressive loss of neural tissue and neurologic function. "PLD1 is considered to be a promising therapeutic target for the treatment of various autoimmune and degenerative diseases." (PMID 32370217, 2020). "To understand the impact of PLD ablation in a neurodegenerative disease C. elegans model, we crossed pld-1 animals with the CL2355 strain, which overexpresses human Aβ in neurons." (PMID 29476137, 2018). "Our work about the role of PLD1 in dendritic spine development indicates that PLD1 should also correlate with neurological disorders including neurodevelopmental diseases and neurodegenerative diseases." (PMID 28729535, 2017).
cardiovascular disease (2 papers, 2019 to 2020). "Meanwhile, genetic deletion or pharmacological inhibition of PLD1, PLD2, or both of PLD1 and PLD2, did not result in a prolonged bleeding time, suggesting that PLD inhibition might be a safe strategy to prevent cardiovascular diseases." (PMID 32971863, 2020).
heart disease (1 paper, 2023). "From previous reports, the PLD1 mutation with cardiac disease is only homozygous, which is consistent with our report." (PMID 37770978, 2023).
neurological diseases (1 paper, 2017). "Therefore, it is promising to classify PLD1 as a pivotal molecule to modulate the activity of the proteases and neuronal development as well as a novel target for treating neurological diseases." (PMID 28729535, 2017). "Taking together, our results indicate a positive role of PLD1 in synaptogenesis by inhibiting the ADAM10 mediated N-cadherin cleavage and provide new therapeutic clues for some neurological diseases." (PMID 28729535, 2017). "Finally we found that PLD1 promotes the dendritic spine development by preventing N-cadherin from being cleaved by ADAM10, suggesting a potential role of PLD1 as an important regulator and a novel therapeutic target in neurological diseases." (PMID 28729535, 2017).